NRAS (NRAS proto-oncogene, GTPase)
Diseases named in the same sentence as NRAS in open-access papers (continued):
Sharing a sentence is not in itself a finding about the gene and the disease.
melanoma (continued). "Typical driver mutations in melanoma such as BRAF, NRAS, and KIT result in constitutive MEK-ERK-signaling." (PMID 33870460, 2021). "The initial KRAS-mutated melanoma of patient 1 (left) showed only minor differences to the KIT-mutated and NRAS-mutated part of the tumor (middle, right)." (PMID 34072863, 2021). "Another study revealed that combined inhibition of MEK and mitotic regulator Polo-like kinase 1 (Plk1) resulted in significant growth reduction of NRAS-mutant melanoma cells in vitro and also regression of xenografted NRAS-mutant melanoma in vivo." (PMID 33807778, 2021). "Since then, several efforts have been conducted to develop targeted therapy strategies for NRAS mutant melanomas." (PMID 34831002, 2021). "In conclusion, we report a role of the Rho/MRTF pathway in the intrinsic resistance of NRAS mutant melanoma cells to MEK inhibitor-induced cell death." (PMID 33921974, 2021). "In patients with NRAS-mutant melanoma, combined MEK and CDK4/6 inhibitors have demonstrated encouraging therapeutic results." (PMID 34804979, 2021). "RAC1 sets off increased PI3K/AKT signaling in NRAS mutant melanoma, resulting in increased cell proliferation." (PMID 33807778, 2021). "Another pan-RAF inhibitor (PRi, Amgen Compd), in combination with trametinib, demonstrated anti-proliferation properties in vitro in NRAS mutant melanomas." (PMID 34831002, 2021). "Melanoma, a cancer originated from melanocytes, frequently presents mutations in the MAPK pathway, mainly in BRAF and NRAS proteins, at incidences up to 52% and 28%, respectively, according to The Cancer Genome Atlas Network." (PMID 34885944, 2021). "Studies targeting BRAF, NRAS and KIT showed KIT as the most common mutated gene in urogenital tract melanomas, with a mutation frequency higher than 25%." (PMID 33525348, 2021). "While both BRAF and NRAS are members of the MAPK pathway, melanoma tumors with these different mutations have divergences in terms of tumor aggressiveness, drug response, age of onset, and correlation with melanoma subtype." (PMID 35008307, 2021). "Potential determinants relevant for the optimal screening MRI scan interval are melanoma location and type, metastatic sites, BRAF‐ and NRAS‐mutational status, and LDH‐level at diagnosis." (PMID 34741440, 2021). "Apoptosis can be induced in M202 and M207 apoptosis-resistant NRAS-mutant melanoma lines by treatment with AZD6244, via Axin1 depletion." (PMID 34577571, 2021). "They concluded that, among melanoma patients with an earlier stage tumor, beside SLN negativity, intensive surveillance is required, taking into account BRAF and NRAS mutation status." (PMID 34209415, 2021). "Our study includes data from BRAF-mutant G361 and Hs294T as well as NRAS-mutant SK-MEL-2 melanoma cells." (PMID 33937086, 2021). "Our study demonstrated that patients with advanced NRAS mutant melanoma had lower response rates and worse prognoses when treated with anti-PD-1 monotherapy than wild-type patients." (PMID 34290710, 2021). "Although we did not evaluate the response of healthy tissue, this approach did allow us to detect differences in the mutagenicity of a single UVB exposure among melanomas expressing endogenous levels of mutant NRAS or BRAF." (PMID 34210801, 2021). "All NRAS mutant melanoma cell lines in our panel were less sensitive to trametinib treatment than the BRAF mutant SK-Mel-19 cell line." (PMID 33921974, 2021). "Our results are in accordance with previous reports that demonstrated that a combination of MEK and ROCK inhibitors not only reduced NRAS mutant melanoma cell viability in vitro but also reduced tumor growth in vivo." (PMID 33921974, 2021).
melanoma (continued). "This is important given the critical role of the PI3K pathway in promoting senescence bypass in fibroblasts, as well as in melanoma, where loss of PTEN can cooperate with activated BRAF or NRAS to promote tumor initiation and metastatic dissemination." (PMID 34819350, 2021). "PHA-66752 showed a unique sensitivity in NRAS mutant melanoma in terms of cell migration inhibition and apoptosis induction." (PMID 33918490, 2021). "Clinical trials assessing the efficacy of MEKi PD0325901 (PD901), binimetinib and trametinib as single agents have produced modest results in patients with NRAS-mutant melanoma, highlighting the need for agents that can improve the durability of this response." (PMID 35187538, 2021). "It has been reported that ceritinib enhances the efficacy of trametinib, a MEK inhibitor, in BRAF/NRAS‐wt melanoma cell lines, which makes it plausible that ceritinib would not have any effect in BRAF‐mutated cells." (PMID 34058070, 2021). "Concurrent targeting of both CDK4/6 and MEK resulted in enhanced cell death in both BRAF- and NRAS-mutant melanoma." (PMID 33806615, 2021). "The lack of accurate diagnostic markers in response to therapeutic treatment in BRAF/NRAS-driven melanomagenesis is one of the main challenges in melanoma personalized therapy." (PMID 33723350, 2021). "Melanoma at M1a stage was also a factor associated with increased PFS and OS, while the correlation between NRAS mutation and OS was consistent with evidence reporting that this genetic status is linked to better immunotherapy outcomes." (PMID 33669266, 2021). "USP9X was shown to interact directly with ETS-1 and prevent its proteasomal degradation through deubiquitination, promoting ETS-1 transcriptional activity at the NRAS promoter in melanoma cells." (PMID 34066106, 2021). "In melanoma, widely distributed mutations in BRAF and NRAS genes make most of the technologies suitable for analysis." (PMID 34575876, 2021). "Here, we demonstrate that increased Rho/MRTF-pathway activation correlates with high intrinsic resistance to the MEK inhibitor, trametinib, in a panel of NRAS mutant melanoma cell lines." (PMID 33921974, 2021). "The three most prevalent genes mutated in melanoma are BRAF, neuroblastoma RAS viral oncogene homolog (NRAS), and neurofibromatosis 1(NF1), and all participate in the mitogen-activated protein kinase (MAPK) signaling cascade that regulates cell proliferation." (PMID 34066966, 2021). "While MEKi have shown clinical efficacy, their efficacy as single agents against NRAS-mutant melanoma has been modest." (PMID 35187538, 2021). "Currently, mutations in four different proteins (BRAF, GNAQ/GNA11, cKIT, NRAS) are well known to occur during melanoma formation, and affect the MAPK pathways by disrupting the healthy cells’ response to the emerging oncogenes." (PMID 33730175, 2021). "This led to the development of a selective STK19 inhibitor with preclinical results in vitro and in vivo exhibiting inhibitory effects on NRAS mutant melanomas." (PMID 34831002, 2021). "Oncogenic BRAF, NRAS, NF1 mutations can activate the tyrosine kinase receptor EGFR resulting in enhanced ERK1/2 phosphorylation in melanoma." (PMID 34360915, 2021). "Approximately 60% of adult melanoma patients have identifiable oncogenic mutations in the BRAF gene, whilst another 20% have oncogenic NRAS mutations." (PMID 33996584, 2021). "With the emergence of high-throughput genomic technologies, several commonly mutated genes that play a central role in melanoma tumorigenesis and metastasis, such as BRAF, NRAS, and NF1, were identified." (PMID 33564068, 2021). "In mucosal melanomas, apart from driver mutations affecting the MAPK pathway (e.g., NRAS, BRAF, NF1, and KIT), mutations in CTNNB1 affecting Wnt/β-catenin pathway activation have also been reported." (PMID 34149718, 2021). "We obtained the mutation status of BRAF, NRAS and NF1 for the melanoma samples from the TCGA database." (PMID 34698264, 2021).
melanoma (continued). "For example, the first melanoma oncogene described in 1984 was the NRAS protein, which activates the mitogen-activated protein kinases MAPK) cascade (Pokrywka and Lityńska 2012)." (PMID 33730175, 2021). "BRAF, NRAS, and KIT are three well-known genes associated with melanoma, and BRCA1 and BRCA2 are two representative genes associated with breast cancer." (PMID 33121438, 2020). "For the present meta-analysis, correlations to patients with BRAF, NRAS, and KIT mutations, clinical-pathological characteristics and risk factors correlated to the development of melanoma were grouped together." (PMID 31274706, 2020). "Our findings thus show a new pathway involved in NRAS‐mutant melanoma resistance and provide new opportunities for novel therapeutic options." (PMID 31549767, 2020). "Different studies have linked mutually exclusive mutations in the BRAF, NRAS, C-KIT, and NF-1 genes with the development of melanoma." (PMID 32775409, 2020). "In conclusion, these findings demonstrate that FUT8-AS1 exerts tumor suppressive roles in melanoma via regulating NF90/miR-145-5p/NRAS/MAPK signaling axis." (PMID 34094894, 2020). "Mutations in RAC1 are found in 4–9% of patients and is the third “hotspot” mutation in melanoma, following BRAF and NRAS." (PMID 32092958, 2020). "Recently, two independent whole-exome sequencing studies revealed a novel gain-of-function mutation of Rac1 in sun-exposed melanomas, being the most frequently observed somatic mutation after BRAF and NRAS mutations." (PMID 32351958, 2020). "It was demonstrated also that BRAF and NRAS mutations positively regulate MMP-14 gene expression enhancing tumor growth and melanoma invasiveness in vivo." (PMID 32392801, 2020). "EGFR-directed treatment strategies were introduced in colorectal adenocarcinomas wild-type for NRAS and KRAS and BRAF inhibitor treatment finds application in BRAF V600E mutated malignant melanomas." (PMID 33227073, 2020). "Trametinib is an FDA‐approved, allosteric inhibitor of MEK1/2 used to treat NRAS‐mutant melanoma, both as a monotherapy and in combination with other anti‐cancer drugs." (PMID 31549767, 2020). "Analysis of NRAS and BRAF mutations in stage IV melanoma patients by single reaction ddPCR has shown an overall detection rate of 73%." (PMID 32785074, 2020). "NF1 gene encodes for neurofibromin, a protein that negatively regulates the MAPK pathway: it is the third most commonly mutated gene in melanoma, found in 46% of cases with BRAF and NRAS wild type, and often co-mutated with RAS-associated genes." (PMID 33233603, 2020). "Silvestrol has also been shown to synergize with MEK inhibitors in multiple NRAS-mutant melanoma cell lines." (PMID 32517051, 2020). "The authors show phendione induces DNA damage response without causing DNA breaks or inducing cellular dormancy, therefore blocking tumor growth of BRAF mutant and NRAS mutant melanomas." (PMID 32241802, 2020). "Further analysis of previous sequencing results showed that EZH2 mutations in human melanoma co-occur with activating mutations in BRAF (p = 0.006) and are mutually exclusive with NRAS mutations (p = 0.004)." (PMID 33024276, 2020). "Almost all primary malignant melanomas of the lung are classified into the triple-wild-type, and few are classified into the mutant NRAS type." (PMID 32028967, 2020).
melanoma (continued). "Based on the morphological, immunohistochemical (mainly MelanA and MITF positivity) and molecular features, the diagnosis of metastatic NRAS-mutant melanoma was established." (PMID 33100226, 2020). "The most commonly reported mutations in cutaneous malignant melanomas are located in BRAF and NRAS genes." (PMID 32637031, 2020). "The authors of this study reviewed the TCGA database and identified MAP2K1 alterations in 7% of melanomas, consisting mostly of point mutations with some amplifications and no in-frame deletions, with nearly all co-occurring with BRAF or NRAS mutations." (PMID 32483240, 2020). "Our data show that the TAK1 pathway is involved in resistance toward MEK inhibition in NRAS‐mutant melanoma." (PMID 31549767, 2020). "We also acknowledge that there were only minor differences in MEK signature score by NRAS mutation and clinical response status, limiting the utility of this score as a biomarker for MEK inhibitor response in melanoma." (PMID 31839677, 2020). "Recently, RASA2 and NRAS mutations were confirmed to be mutually exclusive, with NF1 mutations significantly co-occurring with RASA2 mutations in BRAF and NRAS wild-type melanomas, since RASA2 inhibits NRAS and NF1 inhibits KRAS and HRAS." (PMID 32850962, 2020). "Human melanoma cells produce five NRAS isoforms, expressed at different levels, resulting in a varied activation of downstream pathways, levels of phosphorylated p-Erk and p-Akt and resistance to anticancer drugs." (PMID 32764370, 2020). "In general, the BRAF and NRAS status defined the nature of the proliferative apparatus, which has been well established as a major molecular biomarker of melanoma." (PMID 32411243, 2020). "Nelfinavir has been identified as a potent suppressor of PAX3 and MITF expression and sensitizer of BRAF and NRAS mutant melanoma cells to MAPK pathway inhibitors." (PMID 33322354, 2020). "The MAPK pathway that is activated in melanoma as a result of mutations in BRAF, NRAS, or NF1 has been shown to regulate the expression, stability, and activity of a number of different melanoma-relevant transcription factors." (PMID 33024276, 2020). "More recently, new oncogene-targeting chemotherapeutic agents have shown promising effects especially in tumors mutated on KRAS, NRAS and BRAF including melanoma." (PMID 31906480, 2020). "The presence of mutations of NRAS, and KIT genes has also been correlated to the subtype and localization of melanoma." (PMID 31274706, 2020). "The occurrence of BRAFV600+ mutation is associated with an increased pDC density in melanoma metastasis compared with BRAF wild-type tumors, whereas in locally advanced PCM, a collapse of the pDC compartment particularly occurs in NRAS-mutated tumors." (PMID 32731406, 2020). "The majority of melanoma cases demonstrate oncogenic activation of the KIT—NRAS—BRAF—MEK—ERK central axis that is a major regulator of cell differentiation and proliferation." (PMID 32085741, 2020). "Funnel plot analysis demonstrates no bias in published studies which analyse mutations in BRAF, NRAS, and KIT genes for patients with melanoma, according to their sex, melanoma subtype, localization of melanoma, chronic solar exposure, and ulceration." (PMID 31274706, 2020). "Our study aims to evaluate and review other studies that present the frequency of mutations of BRAF, NRAS, and KIT genes for different populations, and analyse correlation to their clinical-pathological characteristics and to the demographics of melanoma." (PMID 31274706, 2020). "Put together, our findings reveal a novel mechanism leading to tumor resistance toward MEK inhibition in NRAS‐mutant melanoma." (PMID 31549767, 2020). "Recently, a preclinical study has described a new combination strategy involving BET inhibitors with MEK inhibitors to overcome drug resistance in NRAS-mutant melanoma." (PMID 31906480, 2020).
melanoma (continued). "Although myosin II activity is controlled by BRN2-mediated downregulation of PDE5A and increased calcium signaling in BRAF mutant melanoma, our mechanism seems operative in NRAS mutant melanoma." (PMID 31935375, 2020). "Our whole‐genome CRISPR‐Cas9 knockout screen identified the target Kelch domain‐containing F‐Box protein 42 (FBXO42) as a factor involved in NRAS‐mutant melanoma‐acquired resistance to the MEK1/2 inhibitor trametinib." (PMID 31549767, 2020). "SCH772984 has shown promising results in a panel of melanoma cell lines, including cells with innate or acquired resistance to vemurafenib, cells with BRAF/NRAS double mutations or NRAS mutations (NCT02457793)." (PMID 32760738, 2020). "RNA sequencing analysis of NRAS‐mutant melanoma patient‐derived cell lines identified FBXO42 to be differentially expressed between resistant and sensitive patients treated with MEK inhibitors." (PMID 31549767, 2020). "In response to ERK and MEK inhibition, AXL/MITF-mediated drug resistance is observed among mutant BRAF and NRAS melanoma cell lines." (PMID 32245042, 2020). "XL888 upregulated BIM and BAX (BCL-2 associated X protein) expression while decreasing protein level of MCL-1 that resulted in apoptosis induction in NRAS-mutant melanoma cells." (PMID 31659567, 2020). "Our patient was surgically treated at the age of 20 for AST and died four years later of metastatic NRAS-mutant melanoma most likely of different occult origin." (PMID 33100226, 2020). "Transcriptome-wide profiling of patient-derived melanoma samples has led to the identification of specific signatures associated with major oncogene subtypes (e.g., BRAF-mutant, NRAS-mutant, NF1-mutant, and triple wild-type) and prognoses." (PMID 33024276, 2020). "Large-scale sequencing efforts have led to the classification of melanoma into four major subtypes (i.e., BRAF-mutant, NRAS-mutant, NF1-deficient, and triple wild-type)." (PMID 33024276, 2020). "As expected, NRAS silencing in melanoma cell lines significantly reduces cell proliferation, migration, and invasion and promotes cell apoptosis." (PMID 33072757, 2020). "For example, NRAS is the most common in melanoma, while HRAS in adrenal glands and KRAS in pancreas." (PMID 31941155, 2020). "Here, a whole‐genome CRISPR‐Cas9 screen identified FBXO42 ubiquitin ligase involvement in resistance to trametinib treatment in the context of NRAS‐mutant melanoma." (PMID 31549767, 2020). "In melanoma, tumour growth is enhanced through activation of the MAPK pathway, which is primarily driven by activating mutations in two oncogenes: BRAF and NRAS." (PMID 33511334, 2020). "To highlight the utility of our platform, we generated substitution mutations in each exon of three human genes (MAP2K1, KRAS, NRAS) associated with resistance to vemurafenib, which is a cancer drug targeting the BRAF V600E mutation in melanoma patients." (PMID 32242071, 2020). "The majority of melanomas harbor point mutations of BRAF, NRAS, KIT, or NF1 that drive tumor growth." (PMID 32123303, 2020). "Two components of the gene signature were investigated by gene silencing in BRAF/NRAS wild-type melanoma cells." (PMID 31839677, 2020). "Melanoma cell growth is typically driven by the ERK/MAPK pathway, which is hyper‐activated in at least 80% of melanomas that occur through mutations in NRAS (~20%), BRAF (~50%) and NF1 (~14%)." (PMID 31323160, 2020). "Mutations in the BRAF, NRAS, and C-KIT genes have been associated with the histopathological characteristics of melanoma." (PMID 32775409, 2020). "In preclinical studies binimetinib inhibited the growth of NRAS and BRAF mutated melanoma tumor cells." (PMID 32850962, 2020).